CXCL10 (C-X-C motif chemokine ligand 10)
Diseases named in the same sentence as CXCL10 in open-access papers (continued):
Sharing a sentence is not in itself a finding about the gene and the disease.
infection (continued). "AM from FP-treated mice showed impaired expression of infection induced TNF-alpha, IP-10 (CXCL-10), and interleukin 6 (IL-6), and AM also showed a trend towards impaired intracellular pathogen control following in vivo infection." (PMID 22651370, 2012). "The quantification of DC recruiters IP-10 (CXCL10), MIP-3α (CCL20) and BRAK (CXCL-14) by ELISA or qPCR in P2Y2+/+ and P2Y2−/− BALFs confirmed lower expression of BRAK at day 10 post-infection in the P2Y2−/− BALFs compared to P2Y2+/+ BALFs." (PMID 23185614, 2012). "Some others such as CCL3, CCR5, CXCL9, CXCL10, CX3CR1 and CCL24 showed a low expression during the infection." (PMID 22905138, 2012). "Mast cell–derived cytokines and chemokines can enhance the migration of dendritic cells (DCs; TNF-α and CCL20) and effector T cells (CXCL10/IP10 and CCL5/RANTES) to the site of infection and to draining lymph nodes." (PMID 22577358, 2012). "In fact, survival of mice infected with the lethal strain of P. berghei ANKA CM increased to 80% in CXCL10−/− and CXCR3−/− mice when compared with the wild type within the observation period of 10–12 days post infection." (PMID 22479586, 2012). "Time course analysis revealed that primary human CBMCs accumulate maximal levels of CCL4 and CXCL10 mRNA and produce CCL4 and CXCL10 in nanogram amounts as early as 12 hours post-infection." (PMID 22479521, 2012). "Consistent with previous studies and associated with the classical activation M1 phenotype, transcription of TNFα (up to 5), CXCL10 (IP10), CCL2 (MIP1α), and other chemotactic cytokines such as CCL3 (up to 6.8) and CCL4 was upregulated following infection." (PMID 22928052, 2012). "Levels of IFNβ, CXCL10 and CCL5 are induced by infection at all time points but the response is impaired in LGP2-deficient cells compared to wild-type." (PMID 21533147, 2011). "Of note, the total fold increase in CXCL10, ISG54 and IFN-Beta mRNA induced in M1 infected cells was significantly higher than that observed in WT cells at both 20 and 24 hours post infection." (PMID 22174679, 2011). "Levels of the cytokine IL-6 and of the chemokines CXCL9, CXCL10, and CCL4 were significantly lower in vaginal washes one day after infection with HSV-2/gD compared with HSV-2/gD-Δ7-15." (PMID 21283640, 2011). "Consistent with the IFN-α secretion observed after MVA and MVA-B infection of MDDC, the present study also described secretion of MIG/CXCL9, which, together with IP-10/CXCL10, is known to be markedly upregulated in the presence of IFN-α." (PMID 21625608, 2011). "In the present study, our goal was to begin to learn how infection with B. burgdorferi stimulates monocytes/macrophages to secrete CCL2, CCL4, CXCL9, and CXCL10." (PMID 20828409, 2010). "In contrast, in X4LAI.04-infected tissues production of CCL3, CCL4, CCL5, CXCL10, and CXCL12 was significantly increased compared with that in uninfected tissues and reached a maximum 5 to 9 days post-infection." (PMID 20862220, 2010). "Accordingly, experimental infection with L. braziliensis leads to increased leukocyte recruitment, CCL2 and CXCL10 expression, and production of IL-10." (PMID 20559550, 2010). "To evaluate the expression of ISGs in response to C. pneumoniae infection, we harvested total RNA from cells receiving bacterial or mock infection for the indicated time intervals and looked for expression of CCL5, ISG56, and CXCL10." (PMID 20386592, 2010). "In summary, at the late phase of infection (i.e. 18 and 24 hours post-infection), TNF-α, IL-6, IL-8, CCL-5/RANTES and CXCL-10/IP-10 mRNA remained at high levels for H5N1/2004 and H9N2/1997; which were in contrast to those observed for H1N1/2002." (PMID 21108843, 2010). "In spite of overall similar cellular responses in both the infections, WB-NIV2664 was found to be a compelling inducer of cytokines CXCL10 and RANTES than IBCDC-RG-7." (PMID 20828378, 2010).
infection (continued). "Although no significant cytokine/chemokine induction was observed during the early phase of H1N1 infection; IP-10/CXCL-10, TNF-α, TGF-β2, CCL-5/RANTES, IL-8, and IL-6 were found to be 4-450 folds induced during the late phase of infection." (PMID 21108843, 2010). "As for H5N1/2004 infection, CCL-5/RANTES and CXCL-10/IP-10 were found to be induced to >1000 folds; whereas TNF-α and IL-8 were expressed at 200-300 folds." (PMID 21108843, 2010). "At 18 hours post-infection, IL-6, CCL-5/RANTES and CXCL-10/IP-10 were highly expressed (12 to >1000 folds) in H5N1/2004 infection." (PMID 21108843, 2010). "During infection with LCMV (Traub), genetic silencing of CXCL10 or its receptor CXCR3 reduces the infiltration of CD8+ T cells, conferring either partial or near complete protection from immunopathology and death." (PMID 20686655, 2010). "During our analysis we found that CXCL10 and CXCL11 were among the most highly induced chemokine genes during infection with both viruses." (PMID 19798428, 2009). "Late infection featured further Th1 reduction, neutrophil accumulation, and NETs activation (H3cit, NE-DNA, MPO), along with reduced CXCL9 but elevated IL-6, IL-21, IL-27, CXCL10, and S100A8 in blood." (PMID 42112327, 2026). "Similarly, proinflammatory cytokines CCL2, CXCL10, and CCL5, etc., were markedly elevated in the infection group." (PMID 41090515, 2026). "Upon infection, OV activates two parallel pathways: the left axis represents the ICD pathway, leading to the release of DAMPs, while the right axis shows the cGAS-STING pathway, upregulating type I interferons and CXCL10." (PMID 40977706, 2025). "The upregulation of ISG15, CXCL-10, ADAM8, and CSF1 was found after infection with vPdR-36U, which could contribute to the generation of mild CSF forms." (PMID 40006915, 2025). "Moreover, STAT1-dependent chemokines including CCL5, CCL8, CXCL10, and CXCL11 showed a slight increase during the early stage of infection, the most significant increase occurred after 10 h.p.i, peaking at 24 h.p.i." (PMID 40934228, 2025). "In addition to type I IFNs, mRNA expression of proteins related to antiviral responses, such as CXCL10, IFIT1, and CCL5, are upregulated after infection." (PMID 39601535, 2025). "4T1 cell infection with SFV upregulated the amount of CCL4 and CXCL10 (p < 0.05)." (PMID 40547518, 2025). "Upon infection, alveolar epithelial cells activate pattern recognition receptors (PRRs), including retinoic acid-inducible gene-I (RIG-I), MDA5 and TLR3, and respond rapidly by releasing type I and III IFNs, IL-6 and chemokines such as CXCL10." (PMID 40969755, 2025). "At day 6 post-infection, multiple indicators of inflammation were noted including increased levels of T-cells, elevated levels of MCP-1 and CXCL10 chemokines in the cerebral spinal fluid (CSF), traumatic brain injury markers MMP-9 and LIF in the thalamus, and activated microglia." (PMID 40005568, 2025). "While Cxcl9, Cxcl10 and Cxcl11 were upregulated, CXCR3 was downregulated post PCN033 infection." (PMID 41295668, 2025). "CXCL10 recruits activated T cells, NK cells, and to a lesser extent, macrophages and dendritic cells to sites of infection, and enhances Th1 polarization by acting on CXCR3 + naïve T cells—establishing a positive feedback loop between IFN-γ-producing Th1 cells and CXCL10-producing resident cells." (PMID 41452432, 2025). "One day after infection, the hemogram is still normal, but circulating TNF-α, IL-1β, and CCL2 were markedly lower in infected hypothyroid mice with respect to euthyroid mice, while CXCL10 levels were higher." (PMID 41263555, 2025). "Furthermore, infection of HeLa cells stably expressing HPV16 E2 with HPV16 virions, resulted in significantly reduced mRNA levels of IFN-β, ISG54, ISG56, and CXCL10 compared to empty vector controls." (PMID 40264759, 2025).
infection (continued). "Concomitantly, genes involved in inflammatory and interferon-related responses, including IFN-γ, IL-12b, STAT1, STAT3, IL-6, TNF-α, CXCL9, CXCL10, and CXCL5, were significantly upregulated, indicating a strong pro-inflammatory environment during peak infection." (PMID 40630939, 2025). "IP-10 (CXCL10) is induced by IFN-γ and is known to recruit T cells to sites of infection." (PMID 41471181, 2025). "To further validate these findings, we knocked down Usp8 in Usp8fl/fl mouse embryonic fibroblast (MEF) cells via infection with Cre lentivirus and found that the EMCV‐induced expression of Ifnb1 and Cxcl10 and the EMCV‐induced phosphorylation of TBK1 and IRF3 were significantly impaired." (PMID 40525588, 2025). "Several additional immune and inflammatory responses were brought out by poly I:C (e.g., ISG15, CXCL10 and OAS) stimulation, and they correspond to the CJ + SEP transcripts identified here, suggesting a common response to infection by very different cell types." (PMID 40434970, 2025). "S. aureus biofilms stimulate CXCL10 chemokine secretion, via the biofilm matrix compound PNAG, which also stimulates NF-κB, Dectin-1 and CARD9 expression, inducing monocyte formation, in turn triggering immune response at the site of infection." (PMID 40745039, 2025). "In addition, expression of the protein-coding genes CXCL10, IFIT1, NCOA7, IFIT2, SIX3, and RPSA was increased during infection." (PMID 40510596, 2025). "In the striatum, we also see clustering within the fentanyl-treated groups based on infection status: EcoHIV-infected mice treated with fentanyl had higher concentrations of CCL2, CCL4, CCL5, and CCL11 but lower levels of CCL3 and CXCL10 than the uninfected, fentanyl-treated animals." (PMID 40447886, 2025). "Although we did not detect a Cxcl10-dependent difference in viral burden at day 4 post infection, it is important to note that we only quantified the viral N gene by qPCR and not replication competent virus." (PMID 39803542, 2024). "WT and HuR KO RAW264.7 cells were infected with 1 MOI HAZV and at 9 h post infection, the expression of Il6, Ifnb, Tnf, Cxcl10, Il10, Il12p40, Ccl2 and Tgfb relative to non-infected control cells and the copy number of S segment inside cells were measured." (PMID 39348382, 2024). "Noteworthy, next to IL-6 and CXCL10, we also investigated whether NSPHs could be triggered to release IFN-α2 and IFN-β upon infection with VZVeGFP-ORF23 or SeVeGFP, as a sign of intrinsic anti-viral response." (PMID 39351233, 2024). "Nevertheless, the upregulation of CXCL10 (at the protein level) or ISG15 mRNA, both of which are induced by type I interferon, indirectly demonstrated the efficient establishment of the IFN response upon infection." (PMID 39345143, 2024). "Our qPCR analysis reveals significantly elevated RIG-I and TLR3 expression in LNCaP cells compared to PANC-1 upon rSFV-infection even in the absence of transgenic-CXCL10 expression." (PMID 38425844, 2024). "Histological findings of immune cell infiltration in tracheal tissues after infection with swH1N1 was in line with induction of cytokines and chemotactic factors (AMCF-II, CXCL8/IL8, CXCL2, CXCL10, and CCL20) as well as receptors (CCR1 and CXCR2) in lower trachea after this infection." (PMID 39247193, 2024). "Indeed, VSVΔ51 infection induced a large cross-section of antiviral genes (IFITs, IFITMs, OASs, ISGs) and different pro-inflammatory cytokines and chemokines (CCL5, CXCL10, IFNB1) that were all downregulated by 4-OI treatment." (PMID 38750019, 2024). "Although IFNβ1 expression in the nose was not increased after intranasal infection, CXCL10 expression was significantly higher upon intranasal infection at 6 dpi." (PMID 39599832, 2024). "The expression of Il6, Ifnb, Tnf, and Cxcl10 after HAZV infection was significantly increased in WT cells, and was not altered by UV-treated HAZV." (PMID 39348382, 2024).
infection (continued). "In our review, we found most frequently increased CCL2 (41.7% in vitro, 45.5% in vivo, and 33.3% in human serum during the acute phase of infection), CCL5 (50% in vitro, 38.6% in vivo), and CXCL10 (41.7% in vitro, 40.9% in vivo, and 33.3% in human serum during the acute phase of infection)." (PMID 38543749, 2024). "Compared to sham-infected and placebo-treated groups, RV-A1-infected and ECSN6-treated animals showed increase in Cxcl2 and Cxcl10 at 24 h post infection but not Tnf-α and Muc5ac." (PMID 39538325, 2024). "When we inhibited NF-κB and TLR3 separately we did not see an increase in CXCL9 and CXCL10 even following infection with our Hsc70-binding viruses." (PMID 38860860, 2024). "Only 2 of the 12 up-regulated ISGs (CXCL10 and IFI16) and 2 of the 4 down-regulated (CLDN2 and MX1) were common between HEV-3c and HEV-3f infection, suggesting that the IFN response might differ depending on the HEV subtype involved in infected swine." (PMID 38058490, 2023). "CXCL10 and ZPB1 were among the top five DEGs in both lineage infections." (PMID 37766362, 2023). "Data on gene-fold change for IFNB1, CCL5, CXCL11, CXCL10, and IDO1 after experimental infection of HLMVEC by pathogenic (ANDV, HTNV) and nonpathogenic (PHV) viruses were recorded at seven timepoints t = 0, 12, 24, 36, 48, 60, 72 hpi." (PMID 37766212, 2023). "Serving as chemokines, CXCL9, CXCL10, and CXCL11 attract the cells with their cognate receptor CXCR3, including neutrophils, monocytes/macrophages, dendritic cells, T cells, and NK cells, to the site of infection." (PMID 37214455, 2023). "In the absence of DNA-PKcs, MVA and dl1043-driven IFNB and CXCL10 transcription were both significantly reduced compared with the infection of wild-type cells." (PMID 38269102, 2023). "In addition, during infection of intestinal cells, there is an altered cytokine profile characterized by upregulation of CCR1, CCR8, IL-16, IL-3, and CXCL10 (IP10), while CCR2, CCR5, and IL-5 can be downregulated." (PMID 37175995, 2023). "We further investigated the possible differences in host defense pathways by RNA-seq analysis and found an increase in some key host defense transcripts, such as IFNL1, IFNL3, CXCL10, and CXCL11, in response to infection with recent EV-D68 isolates compared to Fermon." (PMID 37376591, 2023). "CXCL-10, IL-6, G-CSF, MCP-1, TGF-a, TNF-a, MIP-2-A, BAFF, MDC, TRAIL-R2 and MIP-1-A all had at least 2-fold change from mock-infected wells, although many proteins in the panel showed some degree of upregulation post-infection." (PMID 37766362, 2023). "WNV natural infection in humans can induce high levels of CXCL9 and CXCL10 in the serum." (PMID 36992514, 2023). "Levels of proinflammatory chemokines and cytokines CXCL1, CCL5, IFN-γ, IL-1β, CXCL10, IL-17, TNF-α and IL-6 were also assessed in the brain, spleen and liver of MAYV-infected mice throughout the infection." (PMID 36902230, 2023). "Infection with virulent ASFV isolates often results in exacerbated immune responses, with increased levels of serum pro-inflammatory interleukins (IL-1α, IL-1β, IL-6), TNF and chemokines (CCL2, CCL5, CXCL10)." (PMID 36680273, 2023). "CXCL10 is a chemokine known to chemoattract CXCR3-positive cells, including activated T cells, NK cells, macrophages (microglia cells in CNS), and dendritic cells, toward sites of infection and inflammation." (PMID 37235332, 2023). "To investigate if the other CXCR3 ligand, CXCL10, or the receptor itself are contributing to murine FHL, we treated prf1−/− mice infected with LCMV to induce FHL with a CXCR3 antagonist, AMG487, starting at day 3 post infection (p.i)." (PMID 37516815, 2023). "We conclude that IFNA1, IRF3, CXCL8, CXCL10, IFNB1, and CHUK are the key hub genes involved in the H5N1 human infection, which makes a major contribution towards the inflammation or cytokine storm leading to the prognosis of the disease and critical clinical outcomes." (PMID 37515084, 2023).
infection (continued). "Of the six leopards with unknown infection status, three had positive CXCL9 results along with CXCL10 upregulation." (PMID 37727792, 2023). "Similarly, the expression levels of pro-inflammatory response factors (IL-6, TNF-α, CXCL10, CCL7, CXCL11, and CCL2) were significantly decreased at 6 dpi, as compared to virulent WT infection." (PMID 37623322, 2023). "Elevated levels of key inflammatory chemokines and cytokines, such as CXCL10/IP-10 and IL-1β, were observed in nasal wash fluid and lung homogenate supernatants from hamsters during primary infection, but not after reinfection." (PMID 36633406, 2023). "have shown that primary neurons from human angiotensin-converting enzyme 2 (ACE2)-expressing mice produce cytokines (e.g., interferon-α (IFN-α), C-X-C motif chemokine ligand 10 (CXCL10), CCL2, IL-6, and TNF-α) after infection with severe acute respiratory syndrome coronavirus 2 (SARS−CoV−2)." (PMID 37767094, 2023). "Interferon (IFN)-γ-inducible protein, CXCL10/IP-10, is a member of the CXC chemokine family with pro-inflammatory and anti-angiogenic properties, and plays a role in recruiting immune cells, particularly T cells, to sites of inflammation or infection." (PMID 37374999, 2023). "Again, while not statistically significant, we observed higher levels of activated T cell chemoattractant IP-10 (~1.2 fold; CXCL10), and leukocyte attractants MIP-1α (~8-fold) and MIP-1β (~5-fold) 7 days post-infection, relative to conditions prior to infection." (PMID 38035334, 2023). "Of note, although individuals with COVID-19 infection prior to the 1st vaccination were excluded from this study, we had reported that such individuals showed increased transient IFN-γ, IP-10/CXCL10, TNF-α, and IL-6 responses compared to infection-naïve persons, but only after the 1st vaccination." (PMID 38090597, 2023). "Consistent with SARS-CoV-2 infection of human airway epithelial cells, we observe a rapid proinflammatory response during the early stages (24 h) of infection characterized by an increased expression of multiple cytokines and chemokines (e.g., CCL20, IL-6, CXCL8 and CXCL10)." (PMID 37112842, 2023). "CXCL10 are induced by antigen-presenting cells (APC) and stimulated macrophages during infection that assist chemotaxis, leukocyte migration, cell growth and angiogenesis and recent data determined that it could also restrict MTB replication." (PMID 37149713, 2023). "This study assesses the value of the CXCR3 ligands CXCL9/MIG, CXCL10/IP-10 and CXCL11/I-TAC when used to supplement the standard infection markers C-reactive protein (CRP) and procalcitonin (PCT) in the diagnostic algorithm of neutropenic fever in children with cancer." (PMID 36670590, 2022). "In addition, aged ferrets showed high expression of chemokines (CCL4 and CXCL10) and inflammatory cytokines (IFNB1, IL1B, IL6, and IL7) in the early phase of infection." (PMID 35013229, 2022). "CXCL10 and CXCL11 are chemokine ligands that recruit the leukocytes which drive the IFNγ-response, including Th1 polarisation, leukocyte activation and suppression of infection-induced genes in the urothelium (reviewed)." (PMID 35194151, 2022). "Indeed, infection with IAV led to brisk transcription of viral HA and host CXCL10 mRNA in a 72 h time course, whereas ACOD1 mRNA levels increased only in a subset of tissue pieces." (PMID 35025971, 2022). "Consistent with the observation from the siRNA knockdown or sgRNA knockout of PRMT9, infection of Prmt9CKO peritoneal macrophages with SeV or stimulation with 5’PPP RNA led to a significant increase in the expression of Ifnb1, Ifnα4, and Cxcl10 mRNA compared with that in Prmt9WT macrophages." (PMID 36028484, 2022). "However, a number of genes involved in antiviral defense, inflammatory response, and IFN pathways (i.e., CXCL10, CXCL11, IFIT1, etc.)were commonly upregulated in infected Vero E6 cells and HBECs at later stages of infection." (PMID 35604092, 2022).